MYD88 (MYD88 innate immune signal transduction adaptor)
Diseases named in the same sentence as MYD88 in open-access papers (continued):
Sharing a sentence is not in itself a finding about the gene and the disease.
infection (continued). "Several SNPs were associated with susceptibility to infection and septic shock, one in the univariate analysis (rs6853 at MyD88 gene) and seven with the multivariate model (rs610604, rs6922466, rs7753394, and rs583522 at TNFAIP3 gene; rs6579837, rs73272842, rs3792783 at TNIP1 gene)." (PMID 30813592, 2019). "In order to address the immune response to the infection with C. diphtheriae in BMM, Clec4e- and Myd88-deficient cells, the supernatants were collected at 2, 4 and 20 h post-infection for determination of cytokine secretion, such as G-CSF and IL-6, respectively." (PMID 31057086, 2019). "Replication assays carried out with cells derived from MyD88-deficient mice revealed that after 2 h of infection intracellular CFUs of maximum 0.3% of the inoculum were detectable for all C. diphtheriae strains and the number of intracellular CFUs remained almost constant within 4 h post-infection." (PMID 31057086, 2019). "In contrast, MyD88-deficient mice were protected from weight loss after intratracheal infection." (PMID 30800124, 2019). "Interestingly, however, IL-6 mRNA produced in MyD88-deficient macrophages was minimal after stimulation with poly I:C but was comparable to the level of control macrophages after infection with TMEV." (PMID 29410948, 2018). "The strong pro-inflammatory response of heart-recruited leukocytes may overshadow the effects of MyD88 deficiency in cardiomyocytes on the local leukocyte recruitment and T. cruzi control during acute infection." (PMID 30067739, 2018). "While mice deficient for IL-1R or inflammasome developed ECM after blood stage PbA-infection, MyD88-deficient mice were resistant to ECM after sporozoite PbA-infection, less so after blood-stage infection, pointing to a role of IL-1R1 pathway on the pre-hepatic stage of infection." (PMID 28448579, 2017). "This is in line with data showing that mice with a CD11c-specific deletion of MyD88 display enhanced susceptibility towards infection with C. rodentium, which could be rescued by hydrodynamic injection of a plasmid expressing IL-22." (PMID 28520792, 2017). "Furthermore, the sensitivity to infection in individuals with inactivating mutations in MyD88 wanes with age, suggesting that MyD88 becomes redundant in the adult human response to infection." (PMID 28611775, 2017). "Mice deficient in MyD88 are susceptible to infections with either Mtb or Mav, and we have recently demonstrated that negative regulation of inflammatory signaling by a cellular stress sensor, Keap1, facilitates intracellular growth of Mav in human primary macrophages." (PMID 28806745, 2017). "MyD88-deficiency results in compromised barrier function and enhanced infection initiation." (PMID 28796783, 2017). "Since IFN-γ−/− or IFN-γR−/− mice are more susceptible to infection with African trypanosomes than wild-type mice, it is conceivable that the early mortality of infected MyD88−/−, TLR9−/−, and IL-12p70−/− mice is attributed to, at least in part, the impaired capacity of synthesis of IFN-γ." (PMID 28936213, 2017). "Alternatively, Myd88-dependent host-protective and host detrimental effects may cancel each other out, and further research is needed to clearly define a role for Myd88 in acute fatal infection caused by B. cenocepacia in zebrafish." (PMID 28651010, 2017). "This provides a possible explanation, since decreased MyD88 expression levels may confer reduced NF-kB activation and, consequently, susceptibility to infection by pathogens and development of TB." (PMID 28127112, 2016). "Compared to wild-type mice, MYD88 knockout mice are more susceptible to infection." (PMID 28127112, 2016). "In contrast to humans, the ability of mice to recognize Leptospira LPS and Lipid A through TLR4 and MyD88 independent mechanisms, may explain some of the observed differences between humans and mice regarding susceptibility to infection." (PMID 27486445, 2016). "MyD88-deficient mice are very susceptible to infection with L. major." (PMID 26107286, 2015).
infection (continued). "IL-1β, which also signals via MyD88, has been proposed to be dispensable for host defense as mice deficient in the Nlrp3 inflammasome did not exhibit increased susceptibility to S. pyogenes in an intraperitoneal infection model." (PMID 25756897, 2015). "In this study, we investigated the outcome of a primary H. polygyrus infection in mice deficient in MyD88 signaling, and found that they were more resistant to infection than wild-type C57BL/6 mice and had a higher frequency of IL-4–producing CD4+ T cells following infection." (PMID 25114104, 2014). "Mice with a complete MyD88 deficiency show a strongly impaired antibacterial defense after infection with Klebsiella via the airways caused by a mitigated neutrophil recruitment into the airways associated with strongly reduced local levels of neutrophil attracting mediators." (PMID 25254554, 2014). "Furthermore, MyD88-deficient mice, while highly susceptible to acute infection with virulent L. monocytogenes, are fully protected following secondary lethal challenge when immunized with the ActA-deficient mutant." (PMID 24391507, 2014). "Supporting this hypothesis, we observed that MyD88/STING-deficient macrophages produced low levels of IFN-β eight hours post infection." (PMID 24391507, 2014). "In addition, significantly fewer adult worms remained in the MyD88-deficient host 28 d following infection." (PMID 25114104, 2014). "MyD88−/− mice were used as a positive control for susceptibility to infection." (PMID 24098823, 2013). "Early in infection, fungal burden was higher in MyD88-deficient mice and declined thereafter." (PMID 23853597, 2013). "To identify the type of PRR that is associated with this process, before infection with P. brasiliensis, we treated BMDMs and BMDCs with inhibitors of the key protein adaptors Myd88 and Syk, which are essential for the majority of TLR and CLR signaling, respectively." (PMID 24340123, 2013). "However, patients with MyD88- or IRAK4-deficiencies are highly susceptible to infections by Gram-positive bacteria, while they have normal resistance to Gram-negative bacteria and other pathogens." (PMID 23873783, 2013). "Despite normal cytokine production in the sera, NOD1(−/−) mice were highly susceptible to this infection, as judged by the high parasite load in spleen and heart tissues and succumbed to the infection in a similar way to Myd88 and nitric oxide synthase (iNOS) knock-out mice." (PMID 21869919, 2012). "Therefore, we examined the course of S. aureus catheter-associated biofilm infection in MyD88 knockout (KO) mice." (PMID 22879997, 2012). "Indeed when examined further, we found that mice deficient in MyD88 had enhanced fungal burdens during infection." (PMID 21575914, 2011). "However, OM does improve over time in MyD88-deficient animals, with the majority of MEs clearing NTHi by 42 days (our unpublished observation), suggesting a MyD88-independent response to infection in the ME." (PMID 19656404, 2009). "To test whether TLR signaling was required for immune control of F-MLV, we infected mice heterozygous or homozygous for a null Myd88 allele and analyzed virus levels in the spleens at various time-points post-infection." (PMID 19214214, 2009). "Thus the basis for the difference in susceptibility to infection observed between MyD88−/− and TLR2−/− mice requires further study." (PMID 19936231, 2009). "We conclude that MyD88 dependent signaling contributes to a protective host response against B. pseudomallei at least in part by causing early neutrophil activation and recruitment towards the site of infection." (PMID 18946505, 2008). "Moreover, an intranasal infection with HSV1 showed that only MyD88-/- knock-out cells were highly susceptible to infection; followed by viral migration to the brain, and severe neuropathological signs of encephalitis and mortality by day 10 post-infection." (PMID 19088911, 2008).
infection (continued). "Therefore, it can be proposed that TLR2 may have a detrimental effect on the progression of E. granulosus infection and may also enhance the immune response associated with this infection via the TLR2/MyD88/NF-κB signaling pathway." (PMID 39199394, 2024). "Consequently, mice that lack MyD88 are highly susceptible to infection." (PMID 37155695, 2023). "In addition, MyD88-deficient THP-1 cells fail to induce autophagy despite infections with HSV-1." (PMID 36834833, 2023). "Thus, a decrease in Myd88 production caused by pesticide exposure may lead to immunosuppression, resulting in increased infection rate and ultimately risking the survivability of hives." (PMID 37753094, 2023). "Since the USP7-mediated deubiquitination of MyD88 results in greater stability of MyD88 protein, and an uncontrolled innate immune response always results in greater susceptibility to infection, we speculated that P5091-treated mice would also exhibit less severe inflammatory responses." (PMID 36032091, 2022). "Indeed, MyD88 deficient mice showed to be profoundly susceptible to infection." (PMID 34349744, 2021). "The purpose of this study was to carry out for the first time a survey to investigate the already known and de novo SNPs in TMEM154, CCR5, TLR9 and MYD88 target genes in some flocks reared in Italy, in order to identify variants that could confer resistance to SRLVs infection." (PMID 34372496, 2021). "Previously, Myd88 has been shown to enhance innate immune responses against bacterial infections, and in the present study, we have investigated the effect of Myd88 deficiency on the granuloma morphology and the intracellular distribution of bacteria during Mm infection." (PMID 33559740, 2021). "However, in some combinations with MAL, MyD88 has an effect on the risk of infection." (PMID 33072109, 2020). "As we have previously shown that Tregs are crucial for enhancing anti-fungal Th17 cell response and inflammation control at early and later infection phases respectively, we hypothesized that MyD88 deficiency in Tregs may increase susceptibility to infection and worsen inflammation during OPC." (PMID 33240286, 2020). "Moreover, iPSC-derived macrophages may eventually aid in stabilizing MyD88-deficient patients during pyogenic infections." (PMID 33424861, 2020). "However, there is an increased association between SIGIRR and MyD88 during infection with C. trachomatis infection, suggesting that SIGIRR may also associate with the chlamydial inclusion." (PMID 32210474, 2020). "Additionally, the results of western blot test further demonstrated that LEP and DPEP significantly inhibited the high protein expression of TLR4, TLR7, MyD88 and NF-κB p65 caused by influenza A virus infection, and the inhibitory effect was more obvious on the 3rd day of infection." (PMID 31551774, 2019). "In addition, a strongly reduced cytokine production has been observed in MyD88-deficient mice at 20 h post infection, while cytokine levels were significantly increased in Unc93b1 mutant mice 24 h post infection, indicating the presence of UNC93B1-independent, but MyD88-dependent pathways." (PMID 30846984, 2019). "MyD88-deficiency may partially affect IFNβ secretion during the early macrophage response to S. pyogenes infection, but we obtained similar levels of this cytokine from B6 and MyD88-KO macrophages already at 24 hours post infection." (PMID 29579113, 2018). "For example, MyD88 deficiency significantly increased mouse susceptibility to C. muridarum ascending infection, suggesting that the MyD88-regulated mucosal effectors at either the cervical or uterotubal junction barriers may contribute to the prevention of chlamydial ascension." (PMID 28797102, 2017).
infection (continued). "The importance of TLRs in innate resistance to T. gondii was demonstrated by MyD88-/- mice being acutely susceptible as IL-12-/- mice to infection with avirulent strains of the parasite, and both TLR2 and TLR4 receptors may participate in the host defense against T. gondii infection." (PMID 26528819, 2015). "Similarly, in Drosophila Toll receptors contribute to the activation of NF-κB through the conserved adaptor Myd88; this is associated with an increased resistance to infection which has led to the suggestion that TLR-mediated innate responses share a common ancient ancestry." (PMID 24098508, 2013). "Although patients with MyD88 or IRAK-4 deficiency may recruit neutrophils to the site of infection, they cannot respond to neutrophil-derived IL-1β to amplify the neutrophilic response, providing a potential explanation for their selective predisposition to pyogenic infections." (PMID 23209417, 2012). "Therefore, the high sensitivity demonstrated by the Myd88−/− Trif−/− double deficient mice to infection is in accordance with a role for TLR4 and/or TLR3 in the response against T. cruzi, as these members of the TLR family are the only known to use TRIF as a transducer molecule." (PMID 22496959, 2012). "Because the common adaptor of Toll-like receptor (TLR) signaling, MyD88, has been implicated in immunity to T. gondii and in particular in IL-12 MØ responses during Type II infection, we examined whether ΔROP16-mediated IL-12p40 production was dependent upon this molecule." (PMID 21931552, 2011). "Interestingly, even though its activation is delayed, among the three MyD88 is the most important molecule for host defense against Brucella infection in vivo, since MyD88 knockout (KO) mice are more susceptible to infection when compared to TLR4, TLR2, TLR4/TLR2 KO mice." (PMID 16556309, 2006). "Infection also induced dynamic expression changes in the downstream signaling molecules myeloid differentiation factor 88 (MyD88) and nuclear factor-kappa B (NF-κB) p65 in both tissues." (PMID 42204750, 2026). "A predominant part of the MyD88-driven response is triggered by TLR11/12 recognition of the parasite protein profilin during early stages of infection." (PMID 40299872, 2025). "Lipopolysaccharide exposure leads to the upregulation of MyD88 mRNA at the early blastocyst implantation site, and the inhibition of MyD88-related signaling can be used to prevent infection-induced pregnancy defects in mice." (PMID 40218311, 2025). "Following infection, viral RNA is recognized by RLRs and TLRs, leading to modifications by downstream signaling proteins such as Visa, Tbk1, and Myd88." (PMID 40547011, 2025). "To test this, we UV-treated the virus to a level that ablated expression of mCherry driven by the IE1 promoter in our TB40/E mCherry strain (TB40/E-mCh), then examined MyD88 levels at 72 hours post-infection." (PMID 40638072, 2025). "The virus spread was similar across all conditions up to and including d9 post-infection, but beyond that time point, was significantly higher in cells that had received shRNA targeting MyD88." (PMID 40638072, 2025). "At 0 h post-infection (hpi), PRV infection caused a significant increase in the protein expression of TLR4, MyD88, and NF-κB p65 compared with the blank control group (p < 0.05)." (PMID 40308697, 2025). "As before, levels of MyD88 12 days after infection with WT TB40/E-mCh were still higher than levels in uninfected cells but were markedly lower than in cells infected with UL88-STOP-mCh HCMV." (PMID 40638072, 2025). "MyD88 is slightly upregulated at 4 h post-infection in the DF-1 cells, whereas it is strongly upregulated in the DSK cells." (PMID 40981440, 2025). "Our results indicate that FEBF effectively downregulated TLR4, MyD88, and NF-κB p65 protein expression during the early phase of infection." (PMID 40308697, 2025).
infection (continued). "We observed a similar increase in MyD88 expression after infection with UL88-GalK relative to UL88-Rev at d12 post-infection, similar to infection with the UL88-STOP and WT viruses, respectively." (PMID 40638072, 2025). "MyD88 is expressed in both neurons and glial cells, it contributes to the BBB, and infection caused MyD88+ cell loss." (PMID 39946503, 2025). "Across multiple experiments, we found that protein levels of MyD88 were on average ~4-fold higher after low MOI infection with a UL88-STOP virus vs a similar infection with WT TB40/E." (PMID 40638072, 2025). "Our results show that calf tracheal tissues revealed significantly elevated expression levels of TLR2, TLR4, TLR7, and TLR10, as well as MyD88 after infection with M. bovis, and initiated the innate immunity Toll-like receptor signaling pathway." (PMID 40005807, 2025). "The MyD88 molecule has been extensively studied in infection models and is known for its importance in TLR-dependent pathogen recognition and downstream signaling initiated by IL-1 family cytokines." (PMID 40299872, 2025). "PRV infection upregulated TLR4, MyD88, and NF-κB p65 protein expression during the pre-infection phase, followed by their downregulation after 12 h." (PMID 40308697, 2025). "Remarkably, while wildtype C57BL/6 mice were completely resistant to S.Tm θ infection, Myd88−/− mice were infected by this minimal strain." (PMID 40462990, 2025). "Ankle swelling of MyD88−/− mice with Brucella osteoarthritis was less than in wild-type mice in the early stages of infection, but swelling in the mutant mice was elevated compared with wild-type animals after 7 days." (PMID 39967734, 2025). "Remarkably, whereas the S.Tm θ strain is unable to colonize lymphoid tissues, the host barriers to infection by this strain are broken in both Myd88−/− and Ifngr1−/− mice, or through co-expression of the spv operon effector SpvB." (PMID 40462990, 2025). "At the site of infection, the levels of neutrophil platelet aggregates and activated neutrophils of MyD88(PKO) and DKK1(PKO) mice were reduced." (PMID 40502169, 2025). "Infection with NH/P68 also caused down-regulation of IFNAR1 and NLRP3 receptors, MYD88 adaptor proteins, as well as other molecules involved in modulating receptor signaling pathways (JUN, PELI1, TBK1, and TICAM2)." (PMID 40530033, 2025). "In parallel, the fraction of interferon-producing CD4+ and CD8+T cells in MyD88−/− mice was less than in wild-type mice on days 7 and 14 following infection." (PMID 39967734, 2025). "It is also noteworthy that Myd88−/− mice survived infection, a result that is in line with the known existence of MyD88-independent immunity during T. gondii infection." (PMID 39440975, 2024). "This possibility is suggested by studies showing that c-Jun N-terminal protein kinases, including JNK1, are activated by MYD88 signaling to control innate immunity to infection." (PMID 39602254, 2024). "The fungal loads of the single MyD88 mutant flies significantly increased after infection,as compared to the decreased fungal loads observed in most w [A5001] flies." (PMID 39239739, 2024). "This study's results align with previous studies showing that LPS via the TLR4 pathway in the early phase of infection can activate MyD88, which triggers IRAK signal transduction." (PMID 38049119, 2024). "In the context of E. multilocularis infection, we observed that the TLR4/MyD88/NF-κB signaling pathway remains suppressed in the early stages of infection; however, it becomes activated after eight weeks." (PMID 39749332, 2024). "In contrast, MyD88 and IFNAR1 KO mice exhibited resistance to lethal infection with the mouse-adapted SARS-CoV-2 Delta variant." (PMID 39652608, 2024). "In this study, we evaluated Ghrelin serum levels and changes in TLR4/MyD88/NF-κB pathway proteins and inflammatory factors in AE patients and E. multilocularis mouse models at different stages of infection (-4, -8, and -12 weeks)." (PMID 39749332, 2024).